TRAF6 (TNF receptor associated factor 6)
Diseases named in the same sentence as TRAF6 in open-access papers (continued):
Sharing a sentence is not in itself a finding about the gene and the disease.
metastatic melanoma (1 paper, 2016). A melanoma that has spread from its primary site to another anatomic site. "When compared with the nevus specimens, TRAF6 is overexpressed in both primary and metastatic melanoma tissues." (PMID 26769849, 2016).
muscular dystrophy (1 paper, 2020). Muscular dystrophy (MD) refers to a group of more than 30 genetic diseases characterized by progressive weakness and degeneration of the skeletal muscles that control movement. "miR-125b-5p can target TNF Receptor Associated Factor 6 (TRAF6) (a muscular dystrophy factor) to slow down skeletal muscle atrophy." (PMID 32823859, 2020).
Mycobacterium infection (1 paper, 2023). Infections with bacteria of the genus Mycobacterium. "On this basis, we performed western blotting to detect the expression of TRAF6 under different Mycobacterium infection conditions." (PMID 38016969, 2023). "The empirical findings in this study provide a new understanding of TRAF6 in host-bacterial interactions during Mycobacterium infection and further explain the ability of autophagy to resist pathogenic bacteria." (PMID 38016969, 2023). "To explore the role of TRAF6 during Mycobacterium infection, we first examined the expression of TRAF6 in human peripheral blood from healthy people and active TB patients." (PMID 38016969, 2023). "This led us to explore the possible interaction of TRAF6 and Rab7 in Mycobacterium infection, and further exploration of the role of TRAF6 in Mycobacterium-induced fusion of autophagosomes and lysosomes." (PMID 38016969, 2023). "To assess the binding ability of TRAF6 and Rab7 during Mycobacterium infection, we first determined the colocalization of TRAF6 and Rab7 in BCG-infected BMDMs." (PMID 38016969, 2023).
neuroblastoma (1 paper, 2012). Neuroblastoma (NB) is the most common solid, extracranial childhood tumor. "In SH-SY5Y neuroblastoma cells, misfolded mutant DJ-1 L166P alters rRNA biogenesis inhibiting TTRAP localization to the nucleolus and enhancing its recruitment into cytoplasmic aggregates with a mechanism that depends in part on TRAF6 activity." (PMID 22532838, 2012).
neuroborreliosis (1 paper, 2023). "Interestingly, a recent in vitro study of neuroborreliosis, using human brain microvascular endothelial cells challenged with Borrelia bavariensis, also showed an upregulation of IRAK2 and MYD88, while no significant changes were detected for IRAK1 or TRAF6 expression." (PMID 37319241, 2023).
neuropathic pain (1 paper, 2024). Chronic pain caused by damage to nerve fibers. "In this research, we identified that TRAF6 was a biomarker, and TRAF6 deduction lessened CCI-induced hyperalgesia, microglia activation, and inflammatory reaction in neuropathic pain." (PMID 38995476, 2024).
oral lichen planus (1 paper, 2021). Oral lichen planus is a chronic inflammatory oral condition of unknown aetiology characterized by T-cell-mediated chronic immune response and abnormal epithelial keratinization cycle. "The FOXP3/miR-146a/NF-κB axis was previously reported to modulate the induction and function of CD4+ Treg cells to alleviate oral lichen planus, while other signaling pathways including microRNA-155-IFN-γ loop and FOXP3/miR-146a/TRAF6 pathways are involved in the pathogenesis of oral lichen planus." (PMID 34670484, 2021). "Also, other signaling pathways including microRNA-155-IFN-γ loop and FOXP3/miR-146a/TRAF6 pathways were reported to be involved in the pathogenesis of oral lichen planus." (PMID 34670484, 2021).
osteonecrosis (1 paper, 2024). A none disease characterized by death of bone tissue due to a lack of blood supply. "EP300, TRAF6, STAT1, JAK1, CASP8, and JAK2 have exhibited significant differences in SANFH (spontaneous osteonecrosis of the femoral head)." (PMID 38204239, 2024). "In conclusion, EP300, TRAF6, STAT1, JAK1, CASP8, and JAK2 exhibit significant differences in SANFH (spontaneous osteonecrosis of the femoral head)." (PMID 38204239, 2024).
peripheral nerve injury (1 paper, 2023). Injury to a peripheral nerve. "Downregulation of miR-146a-5p in the spinal cord has been reported in rats with neuropathic pain induced by spinal cord injury or peripheral nerve injury, while enhancing miR-146a-5p expression attenuated neuropathic pain by suppressing TNF receptor associated factor 6 (TRAF6) signaling." (PMID 37048131, 2023).
prostatic hyperplasia (1 paper, 2020). "TRAF6 was confirmed to regulate stromal cell proliferation through the Akt/mTOR signaling pathway in prostatic hyperplasia." (PMID 32724313, 2020).
pterygium (1 paper, 2025). A wedge-shaped fibrovascular lesion arising from the bulbar conjunctiva and extending to the cornea. "To elucidate the molecular mechanism underlying MCPIP1’s inhibitory effect of MCPIP1 on pterygium growth, we employed protein interaction prediction tools available on the BioGRID platform and successfully identified TRAF6 as an interacting partner." (PMID 40238115, 2025). "Based on this evidence, we examined the impact of MCPIP1 on TRAF6 ubiquitination in pterygium fibroblasts." (PMID 40238115, 2025). "Consequently, we hypothesized that MCPIP1 potentially modulates the fibrosis process of the pterygium through the autophagy pathway mediated by TRAF6." (PMID 40238115, 2025).
pulmonary hypertension (1 paper, 2025). Increased pressure within the pulmonary circulation due to lung or heart disorder. "Our results are in line with a previous report confirming that hypoxic pulmonary hypertension injury could be aggravated by activating the TRAF6/NF-κB/HIF-1α pathway." (PMID 40666114, 2025).
pyometra (1 paper, 2016). "Constitutive transcription of MyD88-dependent (MyD88, TRAF6, NFKβ) and independent (TRAM, TRIF, IRF3) pathway components was detected in healthy diestrous and pyometra endometria." (PMID 27829462, 2016).
Respiratory tract infection (1 paper, 2021). An infection of the upper or lower respiratory tract. "Probiotic treatment significantly upregulates the expressions of TLR7, MyD88, IRAK4, TRAF6, and NF-κB to alleviate FM1 influenza virus-induced respiratory tract infection." (PMID 33924002, 2021).
rheumatic diseases (1 paper, 2024). "Dysregulation of TRAF6 is linked to rheumatic diseases such as RA, contributing to chronic inflammation, cytokine production, and joint destruction due to overactive TRAF6 pathways and increased bone erosion." (PMID 38675400, 2024). "Dysregulation of TRAF6, as may be observed in rheumatic diseases, can lead to aberrant activation of the NF-κB pathway." (PMID 38675400, 2024).
rheumatic heart disease (1 paper, 2017). An autoinflammatory condition following an infection with Group A Beta Hemolytic Streptococcus (GABHS), in which the heart is attacked by antibodies formed in reaction to a recent GABHS infection. "Taken together, these results confirmed that the MAPKs/TGF-β1/TRAF6 signaling pathway is involved in the development of atrial fibrosis in patients with rheumatic heart disease." (PMID 28323847, 2017).
sarcoma (1 paper, 2018). A usually aggressive malignant neoplasm of the soft tissue or bone. "In line with the mouse data, genetic alterations of TRAF6, including amplification, mutation and deletion, are detected in 1% of human glioblastoma and 3% of human sarcoma (TCGA)." (PMID 30294322, 2018).
synovitis (1 paper, 2012). Inflammation of a synovial membrane. "Our data suggested only subintimal TRAF6 expression correlated significantly with synovitis scores (r = 0.465, P = 0.001) and the inflammatory cell infiltration (r = 0.450, P = 0.002)." (PMID 22656185, 2012). "Here we aimed to investigate TRAF6 expression in RA synovium and its correlation with histological synovitis severity and radiological joint destruction in RA." (PMID 22656185, 2012). "Therefore, we examined TRAF6 expression in RA synovium and analyzed its correlation with clinical disease activity, histological synovitis severity and radiological joint destruction." (PMID 22656185, 2012).
T-cell leukemia (1 paper, 2016). A malignant disease of the T-lymphocytes in the bone marrow, thymus, and/or blood. "In particular, miR-146b-5p has an anti-oncogenic function in the context of PTEN-deficient T-cell leukemia in mice that is mediated by attenuation of TCR signaling through direct repression of TRAF6." (PMID 27550837, 2016).
Thrombocytopenia (1 paper, 2021). A reduction in the number of circulating thrombocytes. "Compared with that in the control group, the expression of TLR7, MyD88, IRAK4, and TRAF6 increased significantly in the B cells of patients with pSS associated thrombocytopenia (p < 0.05)." (PMID 33767707, 2021).
Urea (1 paper, 2025). "Notably, IFNAR1, TBK1, and TRAF6-downstream components of cGAS-STING signaling -were significantly upregulated in the Urea + OGD group, suggesting engagement of DNA damage-driven inflammatory mechanisms." (PMID 41286951, 2025).
Urethral stricture (1 paper, 2025). Narrowing of the urethra associated with inflammation or scar tissue. "In a rat urethral fibrosis model induced by TGF-β1, miR-146a-enriched exosomes derived from TNF-α-treated HUMSC suppressed urethral stricture by reduction of IL-1β/-6, IL-1 receptor-associated kinase 1 (IRAK1), TNF receptor-associated factor 6 (TRAF6), and NF-κB levels in target cells." (PMID 40676634, 2025).
uterine cancer (1 paper, 2018). Primary or metastatic malignant neoplasm involving the uterine corpus and/or the cervix. "A truncation (R335*) and missense mutation (R335Q) at R335 within the coiled-coil domain of TRAF6 are detected in five patients with colon and uterine cancers (TCGA)." (PMID 30294322, 2018).
vasculitis (1 paper, 2018). "By the means of promoter analysis, miR-146a was found to be an NF-κB-dependent gene and base pairs with sequences in the 3′-UTRs of the TNF receptor-associated factor 6 and IL-1 receptor-associated kinase 1 genes, which played an important role in Kawasaki disease-induced vasculitis." (PMID 29903729, 2018).
viral pneumonia (1 paper, 2018). Inflammation of the lung parenchyma that is caused by a viral infection. "In the present study, we find that OMT can significantly decrease the expressions of TLR3, TLR4, TLR7, MyD88, and TRAF6 genes after IAV infection, and we preliminarily speculate that OMT may inhibit IAV proliferation and IAV viral pneumonia via inhibiting TLRs signaling pathways." (PMID 29570670, 2018).
tumor (186 papers, 2006 to 2026). "Tumor necrosis factor receptor-associated factor 6 (TRAF6) is an E3 ubiquitin ligase that plays a crucial role in inflammation, immune responses, and tumor development." (PMID 42121919, 2026). "Tumor necrosis factor receptor-associated factor 6 (TRAF6) is implicated in modulating various critical processes linked to tumor pathogenesis, including but not limited to the regulation of tumor cell proliferation, invasion, migration, and survival." (PMID 38169510, 2024). "TNF receptor associated factor 6 (TRAF6) plays an important role in tumour invasion and metastasis, and has also been associated with regulating autophagy induction." (PMID 37108830, 2023). "In animal models of BCa, administration of pharmacological inhibitors of TRAF2/4 (Std.MD: − 3.36, 95% CI: − 4.53, − 2.18, P < 0.00001) or TRAF6 (Std.MD: − 4.15, 95% CI: − 6.06, − 2.24, P < 0.0001) in mice is associated with reduction in tumour burden." (PMID 36944688, 2023). "TRAF6‐deficient Treg cells resist growth of implanted tumours, abolish immune tolerance in cancer cells and enhance anti‐tumour immunity." (PMID 36881608, 2023). "TRAF6 is involved in myeloid cells development, and overexpression associates with acute myeloid leukaemia growth, suggesting that miRNA-146a acts as a tumour suppressor gene." (PMID 37628949, 2023). "TNF receptor-associated factor 6 (TRAF6) is closely associated with tumor angiogenesis and metastasis." (PMID 35637953, 2022). "To further dissect the role of each arm in regulating the tumor immunotherapy, we applied the Pd-l1-deficient CT26 syngeneic mouse tumor model to block the TRAF6-PD-L1 arm." (PMID 35361799, 2022). "Expression of PD-L1 and MHC-I on surface of tumor cells, and tumor-infiltrating CD8+ cytotoxic T cells were significantly decreased in Usp8/Traf6 double KO CT26 tumors compared with Usp8-deficient CT26 tumors." (PMID 35361799, 2022). "ZC3H12A elicited a reduction in K63-linked ubiquitination and an increase in K48-linked ubiquitination of TRAF6/3, leading to the attenuation of immune recognition and killing of tumor cells." (PMID 35851310, 2022). "Studies in tumor condition indicate that cytosolic legumain interacts with E3 ligase TRAF6 and activates lys63-linked ubiquitination." (PMID 33431801, 2021). "Briefly, in the present study, we investigated the role of TRAF6 played in tumor glycolysis and the underlying mechanisms." (PMID 34409101, 2021). "TAK1 is also activated by TRAF6 through ataxia-telangiectasia mutated (ATM) in DNA-damaged tumor cells." (PMID 33966040, 2021). "As an initiating event, we then looked for a partner of SQSTM1, the K63 deubiquitinase CYLD, which is a tumor suppressor that constitutively regulates the NF-κB pathway by removing K63-linked ubiquitin chains from TRAF6." (PMID 34065348, 2021). "Exogenous overexpression of activated Akt substantially rescinded the glycolysis inhibition caused by TRAF6 knockdown, demonstrating Akt had a critical role for TRAF6 to exert its effect on tumor glycolysis." (PMID 34409101, 2021). "In the present study, we aimed to elucidate the effects of TRAF6 on tumor glycolysis as well as the underlying mechanisms." (PMID 34409101, 2021). "TRAF6 belongs to the tumor necrosis factor receptor-associated factor family and has been demonstrated to be involved in tumor progression in various cancers." (PMID 32724313, 2020). "Here, we report that in addition to baseline defects in the enforcement of immune tolerance, Treg‐specific TRAF6 deficiency leads to impaired Treg function in vivo, heightened anti‐tumor immunity, and resistance to implanted tumors." (PMID 30886050, 2019). "Deficiency of TRAF6 or Skp2 impairs K63-linked ubiquitination, cell membrane localization and activation of Akt, resulting in tumor suppression in mouse tumor models." (PMID 30413706, 2018). "A TRAF6 mutation was present in tumor and adjacent Barrett’s, indicating that the mutation had occurred early in carcinogenesis." (PMID 28531216, 2017).
tumor (continued). "A recent research in cancer has indicated that tumor necrosis factor receptor-associated factor-6 (TRAF6) will promote tumor angiogenesis as it will upregulate the expression of hypoxia-inducible factor-1α (HIF-1α)." (PMID 25089269, 2014). "TLR activation can up-regulate the expression of co-stimulatory molecules and B7 family members through the Myeloid differentiation primary response gene 88 (MyD88)/TNF receptor associated factor (TRAF)-6, resulting in tumor evasion from the immune response." (PMID 24252328, 2013). "There is also one study that revealed TNF receptor-associated factor 6 (TRAF6) as a key player in tumor metastasis regulation through EMT and CSC phenotypes; however, as TRAF6 is the signaling molecule in the TLR3 signaling pathway, a similar effect can be generated with TLR3 stimulation." (PMID 40647457, 2025). "In addition, wogonoside reduced the levels of IL-6, TNF-α, IL-1β and reversed tumor growth caused by overexpression of TRAF6 and its downstream proteins in vivo." (PMID 39654621, 2024). "The TRAF6/NF-κB pathway was linked to TLR4’s role in tumor progression." (PMID 38315263, 2024). "survey found that TRAF6 ubiquitination of K63‐linked chains inhibits tumour progression." (PMID 37859585, 2023). "Furthermore, Traf6 deficiency almost abolished the Usp8-deficient CT26 tumors sensitization to anti-PD-L1 immunotherapy in syngeneic mouse tumor model." (PMID 35361799, 2022). "Moreover, TGF-β through SMAD, DAXX/HIPK and TAK1/TRAF6 signaling pathways, induced apoptosis and caused cell death, and tumor progression." (PMID 36518397, 2022). "So far, the underlying mechanisms by which TRAF6 was upregulated in tumor tissue are largely unknown." (PMID 34409101, 2021). "Moreover, Ki67, an important biomarker of cell proliferative potential, was also substantially impaired in TRAF6-deficient tumor tissue." (PMID 34409101, 2021). "Here, we found that TRAF6‐deficient Tregs were dysfunctional in vivo; mice with Treg‐restricted deletion of TRAF6 were resistant to implanted tumors and displayed enhanced anti‐tumor immunity." (PMID 30886050, 2019). "Given that TRAF6 deficiency in Tregs effectively prevented the establishment of tumor‐enforced immune tolerance, pharmacological targeting of TRAF6 may be a potent means to improve anti‐tumor immunity." (PMID 30886050, 2019). "Additionally, the dysfunction of TRAF6‐deficient Tregs in our tumor experiments was found to be associated with this uncharacteristic distribution of FOXP3 protein." (PMID 30886050, 2019). "The combined knockdown of TRAF6 and NUMB showed that NUMB does not seem to act in an additive or counteractive manner with TRAF6 during tumor suppression; it would suggest that TRAF6 and NUMB are likely to mediate independent cascades causing tumor suppression." (PMID 24302991, 2013). "Meanwhile, TLR signaling, particularly through TLR2 and TLR4, is activated by microbial components and proinflammatory signals in the tumor microenvironment, recruiting adaptor proteins such as TNF receptor-associated factor 6 (TRAF6)." (PMID 41419456, 2025). "Inhibition of CCL3 signaling (via CCR5 blockade) led to significant decreases in TRAF6 and NF-κB activation and a corresponding drop in tumor cell proliferation." (PMID 41153795, 2025). "Transfection of dominant-negative TRAF6 (Traf6 DN) completely inhibited NF-κB transcriptional activation in control (CMTM4 wild-type) tumor cells." (PMID 39948411, 2025). "Although p62 was shown to regulate NFκB signaling in tumor cells via interaction with receptor-interacting protein-1 (RIP1) and TNF receptor-associated factor-6 (TRAF6), its role in the context of autophagy is still debated." (PMID 40460555, 2025). "Multiple studies have demonstrated that TRAF6 participates in a variety of signaling pathways and regulates tumor cell proliferation, metastasis, immune response, and survival." (PMID 40296903, 2025).